INS (insulin)
Diseases named in the same sentence as INS in open-access papers (continued):
Sharing a sentence is not in itself a finding about the gene and the disease.
Hypoglycemia (continued). "In the current study, we recruited adult subjects with normal awareness of hypoglycemia, who were undergoing an insulin-induced hypoglycemic challenge as part of their clinical care." (PMID 33277531, 2020). "Hypoglycemia is a common and serious side effect of insulin therapy in subjects with type 1 diabetes (T1D)." (PMID 33374113, 2020). "Predictive low-glucose management system, the MiniMed 640G System (Medtronic, Northridge, CA, USA), suspends basal insulin delivery with the hypoglycemia prediction algorithm." (PMID 33042005, 2020). "A series of studies have been conducted to ensure the effects of CB on the counterregulatory response to hypoglycemia in an insulin-controlled condition." (PMID 32698380, 2020). "It is difficult to conclude from these studies that it is due to insulin, since these animals also had hypoglycemia." (PMID 32150819, 2020). "On the other hand, insulin overdosing can drive in short time to hypoglycemia, i.e., BG concentration <70 mg/dL, which if prolonged and severe can increase the risk of seizure, coma or even death." (PMID 32664432, 2020). "Further development in technology of integrated closed-loop systems provides algorithm-derived automated adjustment of insulin delivery to address both hypoglycemia and hyperglycemia." (PMID 31953687, 2020). "The present study showed that the risks of MACEs and hypoglycemia were similar in type 2 DM (T2DM) patients treated with basal insulin compared to TZDs and DPP-4is as an add-on to dual OHA combination therapy." (PMID 32238842, 2020). "Glucagon is used acutely to treat insulin-induced hypoglycemia, but its chemical and physical instability in solution has been a serious limitation for its use for extended periods of time in hormone pumps." (PMID 32735622, 2020). "Four patients received intravenous insulin with fasting and had a rapid reduction in triglyceride levels by 65–77% within 24 h; one patient had mild hypoglycemia secondary to therapy." (PMID 33291273, 2020). "At the time of hypoglycemia (0.9 mmol/L) insulin and C-peptide levels were increased (insulin, 55.9 μU/mL; C-peptide, 2.2 ng/mL), Serum ketones were negative and acyl carnitine levels were low leading to the diagnosis of hyperinsulinism." (PMID 32537058, 2020). "Severe hypoglycemia was prevented, and measurement of serum levels of insulin and further lab diagnostics were performed much faster, while the patient’s individual burden caused by invasive procedures was reduced." (PMID 33275114, 2020). "Evidence of raised insulin concentrations at the time of hypoglycemia will confirm the clinical suspicion of protein sensitive HH." (PMID 32185602, 2020). "In contrast to 2DG-induced glucose deprivation and in keeping with clinical testing using insulin-induced hypoglycemia, plasma GH was significantly increased by acute insulin-induced hypoglycemia (mean blood glucose: 51.7 mg/dL; 2.87 mmol/L)." (PMID 33148883, 2020). "Increased CBF in response to insulin-induced hypoglycemia is well documented in the literature but previous human studies were conducted under steady-state conditions using glycemic clamp." (PMID 33277531, 2020). "Both Metformin and Insulin can lead to hypoglycemia, which is the most common side effect of glucose-lowering drugs in general." (PMID 32983560, 2020). "It is well established that the brain regulates glucose homeostasis by several mechanisms, including changes in insulin secretion, the response to hypoglycemia, and glucose handling in the liver." (PMID 32229720, 2020). "As the key element, HH is defined as simultaneous hypoglycemia and detectable serum or plasma (p-) insulin, i.e. ≥2–3 mU/L depending on the assay used." (PMID 33679602, 2020). "Reduced cerebral glucose delivery occurs during hypoglycemia, a condition considered as a major complication of insulin treatment in type 1 diabetes mellitus (DMT1) patients." (PMID 33173467, 2020).
Hypoglycemia (continued). "A similar finding was shown in patients who achieved adequate hypoglycemia with a single or repeated dose of insulin (94.3 vs. 80%, P = 0.021)." (PMID 32328036, 2020). "The VMN is also a plausible site of the estrogenic control of glucostasis as the local administration of estradiol alters insulin-induced hypoglycemia in OVX female rats." (PMID 32188013, 2020). "The results of SMBG inform decisions about immediate rapid-acting insulin doses, planning before and throughout exercise, and the treatment of hypoglycemia." (PMID 32256447, 2020). "Hypoglycemia is one of the most frequent adverse events in intensive insulin therapy for patients with T2DM." (PMID 33015194, 2020). "The initiation and intensification of insulin therapy are usually difficult and challenging with respect to achieving tight glycemic control and preventing hypoglycemia." (PMID 32887578, 2020). "Congenital hyperinsulinism (CH) is a rare disease, characterized by severe hypoglycemia induced by inappropriate insulin secretion from pancreatic beta-cells in neonate and infant." (PMID 31916119, 2020). "During fasting when circulating glucose and arginine levels are lower, insulin level needs to be lowered as well to prevent hypoglycemia." (PMID 32901087, 2020). "A meta-analysis of oral antidiabetic drugs and insulin in GDM reported highest incidence of neonatal hypoglycemia with glyburide." (PMID 33403188, 2020). "The bedtime BG measurement is used to assess the adequacy of the dinnertime dose of insulin and to inform decisions aimed at preventing nocturnal hypoglycemia." (PMID 32256447, 2020). "CGM data analysis revealed that all participants on insulin secretagogue therapy experienced more than one episode of hypoglycemia, especially during the night." (PMID 32151247, 2020). "Insulin-induced hypoglycemia increased plasma GH in mice in keeping with the findings in humans, where insulin-induced hypoglycemia is the gold standard test for somatotrophic axis function in clinical practice." (PMID 33148883, 2020). "Hyperinsulinism (HI) is a rare group of disorders characterised by dysregulated insulin secretion leading to unpredictable hypoglycaemia." (PMID 32580746, 2020). "Impaired awareness of hypoglycemia is an acquired complication of insulin treatment, whereby the potency to detect the onset of hypoglycemia is decreased or absent." (PMID 33042005, 2020). "Fifteen patients experienced more than one moderate hypoglycemia episode during the 2~3 weeks of intensive insulin therapy." (PMID 32149152, 2020). "In this section, we introduce two types of DSSs: insulin therapy adjustments and hypoglycemia prevention." (PMID 32517068, 2020). "Systematic reviews have demonstrated the superiority of rapid acting insulin over Regular insulin as it produces less nocturnal hypoglycemia, better glycemic control and improved patient satisfaction." (PMID 32957991, 2020). "In T2DM patients with poor glycemic control, the application of mobile enabled intervention (LCCP) along with insulin significantly reduced the hypoglycemia while improving glycemic control during period of naïve initiating insulin therapy." (PMID 33224195, 2020). "Malkani and Kotwal have a similar view, wherein they explained the higher incidence of hypoglycemia in young patients with T2DM as a result of higher insulin sensitivity." (PMID 33015194, 2020). "In clinical studies, insulin-induced hypoglycemia increases GH even in individuals with GHRH insensitivity." (PMID 33148883, 2020). "Overall, GH peaks elicited by insulin-induced hypoglycemia and dexamethasone were extremely similar to each other and higher than those recorded in patients previously tested with AST." (PMID 33362716, 2020). "In Wistar rats, insulin-induced hypoglycemia augmented minute ventilation and CO2 sensitivity, but these effects were abolished by the blocking of the sympathetic pathways." (PMID 32698380, 2020).
Hypoglycemia (continued). "In one study, the clinical pharmacist was allowed to adjust insulin doses in naïve patients based on hypoglycemia signs/symptoms." (PMID 32022107, 2020). "Parallel to PanNET formation, MPR mice gradually developed hypoglycemia and increasing serum insulin levels, while MP mice maintained relatively stable blood glucose and serum insulin levels at all ages." (PMID 31160716, 2020). "This creates a ‘shoulder effect,’ whereby the duration of action of the short-acting insulin is prolonged after a meal, increasing the propensity for hypoglycaemia due to unwanted prolonged glucose-lowering action." (PMID 32290465, 2020). "In one retrospective review of 25 infants, three met clinical criteria for hyperinsulinism with hypoglycemia and inappropriately elevated insulin or C-peptide." (PMID 32832707, 2020). "Once initiated, insulin doses are adjusted frequently throughout the pregnancy based on blood glucose results, symptomatic hypoglycemia, physical activity, dietary consumption, infection, and compliance." (PMID 33371325, 2020). "Extensive therapy, especially insulin therapy, can increase the incidence of hypoglycemia, which is one of the most common and unpredictable effects of insulin therapy." (PMID 32771061, 2020). "In comparison to different combinations of metformin, glyburide and bedtime insulin, metformin plus bedtime insulin seems superior with respect to improvement in glycaemic control, frequency of hypoglycaemia and weight gain." (PMID 32316649, 2020). "The instillation of coated prototypes with SL resulted in hypoglycaemia that was accompanied by increased insulin serum levels." (PMID 32178442, 2020). "The use of insulin pump can decrease nocturnal hypoglycemia, and this is further decreased using sensor-augmented pump with the control algorithms, which can suspend basal insulin delivery with sensor-detected or sensor-predicted hypoglycemia." (PMID 33042005, 2020). "In our study, diabetic patients with HbA1c levels < 6.5% are less commonly taking insulin therapy than those with HbA1c ≥ 6.5% (9.5 vs. 30.3%, P < 0.001) to prevent hypoglycemia." (PMID 33344465, 2020). "In general, the combination of conventional OADs with an insulin secretagogue should be avoided in some populations in the case of hypoglycemia." (PMID 32656265, 2020). "Insulin/glucose-ratio during hypoglycemia was 1.6 ± 5.5 mU/l/mg/dl and the mean of highest glucose infusion rate was 14.5 ± 3.8 mg/kg/min." (PMID 33424766, 2020). "In contrast to intrinsic sympathoactivating properties of insulin, acute sympathoactivation leading to norepinephrine release in pivotal brain areas occurs following severe hypoglycemia." (PMID 33292431, 2020). "These beneficial effects on glucose variability are likely achieved in large part due to decreased insulin dosages leading to less pronounced glucose peaks, and less offshoot effects by hypoglycemia, since SGLT2i mainly increase renal glucose excretion." (PMID 33195459, 2020). "During insulin-induced hypoglycemia in vivo or in aglycemia in acute brain slices, glutaminolysis supports the maintenance of microglial process motility and damage-sensing functions." (PMID 32214088, 2020). "Would analog insulin reduce the occurrence of dangerous hypoglycaemia in East Africa and thus encourage patients and families to be more aggressive with insulin dosing?" (PMID 32704558, 2020). "All five praliciguat-treated participants who experienced hypoglycaemia were among the eight taking concomitant insulin, as was one of two placebo-treated participants who reported this adverse event." (PMID 31858186, 2020). "In contrast, insulin-induced hypoglycemia is known to be a potent stimulus for GH release in humans." (PMID 32644973, 2020). "Better glycemic status and prevention of weight gain and hypoglycemia with reduced insulin dosage are the desirable outcomes expected from a new add-on therapy for T1D." (PMID 31935938, 2020).
Hypoglycemia (continued). "The HH group had significantly higher serum insulin levels during hypoglycemia compared to the KH group (p < 0.001)." (PMID 33133020, 2020). "Enteral administration of a mixed meal or oral glucose load followed by hypoglycemia with a detectable insulin within 2–5 h, indicates incretin mediation leading to postprandial HH." (PMID 32185602, 2020). "Although repeated insulin-induced hypoglycemia reduced blood glucose further (mean blood glucose: 40.2 mg/dL; 2.2 mmol/L), there was no significant increase in plasma GH." (PMID 33148883, 2020). "GHRH neuron activity is decreased by both repeated 2DG and insulin-induced hypoglycemia, suggesting cells other than GHRH neurons likely maintain feeding with repeated insulin hypoglycemia." (PMID 33148883, 2020). "To confirm that hypoglycemia also increased eNOS O-GlcNAcylation in vivo, we measured the blood glucose concentration of rats after insulin injection." (PMID 33168911, 2020). "Hospitalization is often required for administration of extremely high doses of insulin, or for monitoring severe and difficult to control hypoglycemia that is related to high mortality rates." (PMID 32813762, 2020). "In the near future, we will try to incorporate the proposed metric and other factors including insulin dosage, carbohydrates intake, and daily activities to improve the specificity and sensitivity of hypoglycemia prediction." (PMID 33204733, 2020). "Here we report a case o af non-pancreatic neuroendocrine tumour (NET) on lung secreting insulin for whom we used prednisone for symptomatic treatment of hypoglycemia." (PMID 34394252, 2020). "TCDD-exposed males displayed modest fasting hypoglycemia for ~4 weeks post-injection, reduced fasting insulin levels for up to 6 weeks, increased insulin sensitivity, decreased beta cell area, and increased delta cell area." (PMID 31996693, 2020). "This insulin’s inhibitory effect appears to be reversed by insulin-mediated hypoglycemia as the lowest glucose levels were observed 1 h post i.p. insulin injection in our preparations." (PMID 33293550, 2020). "DSME encompasses skills such as how to conduct SMBG, how to recognize hypoglycemia, and insulin administration technique." (PMID 31923179, 2020). "Insulin-LMWP conjugates mucoadhesive nanoparticles showed an oral insulin bioavailability of 17.98 ± 5.61%, as well as enhanced hypoglycemia effect by two-fold higher than the nanoparticles loaded-mere insulin." (PMID 33066443, 2020). "Treatment-induced hypoglycemia is known to negatively impact the patient’s adherence to insulin treatment." (PMID 31935938, 2020). "In postprandial hyperinsulinemic hypoglycemia (PPHH), hypoglycemia is induced hours after meal intake due to inappropriate/exaggerated insulin secretion in response to the meal." (PMID 32185602, 2020). "Congenital hyperinsulinism (CHI) is characterised by dysregulated insulin secretion which can lead to life‐threatening hypoglycaemia." (PMID 31577849, 2020). "Another study demonstrated the prolonged stimulatory effect of insulin on HPA secretory activity, preventing the development of hypoglycemia-associated counter regulatory failure." (PMID 32187262, 2020). "In both unadjusted and adjusted analyses, patients treated with sulfonylurea, basal insulin, and basal plus bolus insulin regimens experienced incrementally increasing rates of hypoglycemia-related ED visits and hospitalizations." (PMID 31922562, 2020). "Serum GH responses to insulin-induced hypoglycemia were marginally low in only one child, although the timing of the sample during a two week hospitalization was not specified." (PMID 33117295, 2020). "Insulin pumps or glucose sensors appeared cost-effective, particularly in populations with higher HbA1c levels and rates of hypoglycaemia." (PMID 32746937, 2020). "But smaller doses of insulin should have a lower chance of inducing hypoglycemia according to our clinical experience." (PMID 32328036, 2020).
Hypoglycemia (continued). "We categorized DSSs into those that provide advice on insulin adjustment and those that provide guidance on hypoglycemia prediction and prevention." (PMID 32517068, 2020). "Hypoglycaemia is a known complication of insulin treatment and is acknowledged as the main limiting factor for achieving tight glycaemic control." (PMID 31984443, 2020). "On the one hand, type I ketosis cows are in the hypoglycemia situation because of their high energy requirements and insufficient feed intake, and blood sugar stimulation to islet B cell is relieved, thus INS secretion is inhibited." (PMID 32054179, 2020). "Only one case of hypoglycaemia was reported but that particular patient was on Saxagliptin/Metformin, Gliclazide and basal insulin concurrently." (PMID 32566235, 2020). "This steatosis was concomitant to anorexia, hypoglycemia and a paradoxical transient insulin release." (PMID 32694515, 2020). "The effects of subcutaneous administration of processed shilajit together with insulin on plasma glucose level in streptozotocin-induced diabetic rats demonstrated the reinforcement impact on the insulin-induced hypoglycemia." (PMID 34466583, 2020). "About 19.3% of the patients required insulin infusion for glycemic control with the incidence of hypoglycemia of 8%." (PMID 32908696, 2020). "Animals from both groups behaved similarly during the hypoglycemia period before glucose recovery suggesting the similarly reacted to insulin." (PMID 33173467, 2020). "Exogenous insulin administration promotes somatostatin secretion, which aggravates hypoglycemia by reducing cAMP formation; while somatostatin receptor antagonists improve hypoglycemia by increased cAMP, and associated reduction in oxidative stress." (PMID 32774668, 2020). "The only adverse event related to therapy was observed in Case 6, who had mild hypoglycemia (3.8 mmol/L) during intravenous insulin therapy and was managed by increasing the intravenous glucose infusion." (PMID 33291273, 2020). "We further analyzed the effects of specific types of oral hypoglycemia agent and insulin usage on immunosenescence." (PMID 33088331, 2020). "Insulin therapy was an independent predictor of cesarean delivery, preeclampsia, stillbirth, and neonatal hypoglycemia among our cohort." (PMID 32987806, 2020). "At present, for the treatment of PCOS patients, clinical treatment mainly includes hypoglycemia, insulin and menstrual regulation and other symptomatic and supportive treatment." (PMID 33371158, 2020). "Ghrelin has been implicated in glucose homeostasis, with higher levels shown to prevent hypoglycemia and lower insulin release." (PMID 33348678, 2020). "There is a shifting trend toward outpatient evaluation of patients with symptomatic hypoglycemia using a prolonged overnight fast with repeat morning glucose measurements and formal testing for insulin and C-peptide levels once the glucose level is low." (PMID 32605595, 2020). "Although 13% (5/39) of patients had episodes of hypoglycemia, both the patients and the CNS participants felt that telemonitoring increased efficacy and patient safety in the transition to insulin therapy." (PMID 32406854, 2020). "In the EDITION randomized clinical trial programme, glycaemic control and hypoglycaemia were evaluated by comparing the efficacy and safety of Gla‐300 versus Gla‐100 insulin in patients with T2DM." (PMID 32704550, 2020). "Two studies have compared hypoglycemia incidence in patients with CKD receiving 5 U versus 10 U of insulin." (PMID 33328554, 2020). "Insulin injections are intended to induce excessive hypoglycemia, which leads to a major stress response of the body, with increases in ACTH, cortisol and GH levels, and activation of the sympathetic nervous system." (PMID 32187262, 2020). "Repeated 2DG increased SST+ terminals on GHRH neurons, but SST+ terminals on GHRH neurons were unchanged with repeated insulin hypoglycemia." (PMID 33148883, 2020).